NCAM2 (neural cell adhesion molecule 2)
Description:
May play important roles in selective fasciculation and zone- to-zone projection of the primary olfactory axons.
Synonyms: NCAM21; MGC51008
Tractability: Small molecule: it has a binding pocket of medium quality. Antibody: its Gene Ontology location is reachable by antibodies, with high confidence; UniProt places it where antibodies can reach, with medium confidence; UniProt predicts a signal peptide or a membrane-spanning region; the Human Protein Atlas places it where antibodies can reach. PROTAC: ubiquitination databases record sites on it; its protein half-life has been measured.
Gene: Protein-coding gene on chromosome 21 (20,998,409 to 21,543,329, forward strand). Ensembl gene ENSG00000154654.
Subcellular location: Cell membrane
Subcellular location (Human Protein Atlas): Nuclear bodies; Plasma membrane
Gene Ontology:
Molecular function: identical protein binding
Biological process: neuron cell-cell adhesion; cell adhesion
Cellular component: plasma membrane; membrane; neuron projection; axon; synaptic membrane
Genetic constraint (gnomAD): Loss-of-function variants: 22 observed, 76.09 expected, observed/expected ratio (o/e) 0.29, 90% interval 0.21 to 0.41. The upper end of that interval is the gene's LOEUF score, 0.41, which puts it in group 1 of 6, group 1 being the genes least tolerant of losing a copy. Missense variants: 673 observed, 841.45 expected, observed/expected ratio (o/e) 0.8, 90% interval 0.75 to 0.85. Synonymous variants: 286 observed, 288.46 expected, observed/expected ratio (o/e) 0.99, 90% interval 0.9 to 1.09.
Homologues: Orthologues: chimpanzee NCAM2 (97% identical), macaque NCAM2 (97% identical), rabbit NCAM2 (96% identical), dog NCAM2 (96% identical), pig NCAM2 (96% identical), mouse Ncam2 (94% identical), rat Ncam2 (94% identical), guinea pig NCAM2 (90% identical), tropical clawed frog ncam2 (79% identical), zebrafish NCAM2 (61% identical), zebrafish ncam2 (60% identical). Paralogues in human: NCAM1 (30% identical), CNTN4 (24% identical), CNTN5 (23% identical), SDK2 (23% identical), CNTN6 (22% identical), CNTN3 (22% identical), CNTN2 (22% identical), ROBO1 (22% identical), L1CAM (21% identical), CNTN1 (21% identical), DCC (21% identical), NEO1 (21% identical), and 24 more.
Diseases named in the same sentence as NCAM2 in open-access papers:
NCAM2 is named in the same sentence as 31 diseases in open-access papers, as found by Europe PMC text mining. Sharing a sentence is not in itself a finding about the gene and the disease. The quoted sentences say what the papers report.
Down syndrome (8 papers, 2010 to 2025). "Elevated NCAM2 levels and altered submembrane Ca2+ dynamics are known to cause defects in synapse maturation, as implicated in the pathology of Down syndrome and other brain disorders associated with abnormal NCAM2 expression." (PMID 40548375, 2025). "Studies have shown that NCAM2 is associated with autism and Down’s syndrome, whereas COL4A6 methylation is linked to high genetic risk of development of mood disorders." (PMID 38638145, 2024). "NCAM2 is encoded by a gene located on chromosome 21 in humans, which is triplicated and thereby overexpressed in Down’s syndrome." (PMID 36251052, 2022). "NCAM2 is encoded by a gene on chromosome 21 and is also overexpressed in individuals with Down’s syndrome." (PMID 36251052, 2022). "Alterations in NCAM2 have been associated with different disorders, such as Down Syndrome or Autism Spectrum Disorders." (PMID 34576185, 2021). "Although the gene is poorly characterized in the literature, prior studies have implicated roles of NCAM2 in prion disease, Down syndrome, and AD." (PMID 20932310, 2010). "Our analytic method recovered and synthesized these prior associations by showing that cortical MS increases in Down syndrome are preferentially localized to cortical regions with a strong expression signature for OPCs, which include NCAM2 in their cell-class gene set." (PMID 32620757, 2020). "Due to its location in human chromosome 21, NCAM2 has been proposed as a candidate for the intellectual disability phenotype observed in Down Syndrome." (PMID 34576185, 2021). "It has been reported that NCAM2 was a candidate for involvement in certain Down syndrome phenotypes." (PMID 26064910, 2015). "Although NCAM2 have so far not been associated with cognitive impairment, it has been involved in synaptic deficits in Alzheimer’s disease and was implicated in the intellectual disability phenotype in Down syndrome and autism spectrum disorders, as well as in other neurodevelopmental diseases." (PMID 35602555, 2022). "However, the role of NCAM2 deletion in the pathophysiology of Down syndrome is unknown." (PMID 26064910, 2015).
Alzheimer disease (7 papers, 2015 to 2024). A progressive, neurodegenerative disease characterized by loss of function and death of nerve cells in several areas of the brain leading to loss of cognitive function such as memory and language. "It has been proposed that the early loss of synapses detected in patients with Alzheimer’s Disease could be the result of the β-amyloid-induced proteolysis of synaptic NCAM2." (PMID 34576185, 2021). "Amyloid-beta increases NCAM2 cleavage and reduces its function in synapses, which could explain the synaptic loss observed in early stages of Alzheimer’s disease." (PMID 34299022, 2021). "Some processes controlled by NCAM2 are altered at the early stages of neurodegenerative diseases, such as Alzheimer’s disease." (PMID 34576185, 2021). "Neural cell adhesion molecule 2 (NCAM2) protein has been shown to reduce inflammation in Alzheimer’s disease." (PMID 33194371, 2020). "Genetic studies established a relation between NCAM2 and Alzheimer’s Disease." (PMID 34576185, 2021). "In addition, NCAM2 has been involved in synaptic deficits in Alzheimer’s disease." (PMID 34299022, 2021). "Due to the pivotal role of NCAM2 in synaptic structures and the mentioned interactions of NCAM2 with the cytoskeleton, the ablation of NCAM2 in synapses could lead to major changes in cytoskeleton structures, thus compromising synaptic viability in Alzheimer’s Disease." (PMID 34576185, 2021).
autism (4 papers, 2018 to 2024). Persistent deficits in social interaction and communication and interaction as well as a markedly restricted repertoire of activity and interest as well as repetitive patterns of behavior. "Previously, NCAM2 was proposed as a candidate gene for autism based on genome-wide association studies." (PMID 34992628, 2021). "Under this perspective, it may be useful to here recall some of the results on the localization of the neural cell adhesion molecule 2 (NCAM2) in the Reeler mouse because the molecule has also been proposed as a predisposition gene for the development of autism." (PMID 31805691, 2019). "NCAM2 also has been suggested as a candidate gene for autism because it is highly expressed in the brain and nervous systems." (PMID 31061677, 2018). "Duplications, deletions, and single-nucleotide polymorphisms of the NCAM2 gene have been found in individuals with intellectual disabilities or autism, and these studies suggest that NCAM2 might play a role in neurodevelopmental disorders." (PMID 34992628, 2021).
Cognitive impairment (4 papers, 2022 to 2024). Abnormal cognition is characterized by deficits in thinking, reasoning, or remembering. "The single nucleotide polymorphism (SNP) of Ncam2, nerve cell adhesion molecule 2, is highly expressed in synapses and correlated with Aβ levels in human cerebrospinal fluid during cognitive impairment in AD." (PMID 39635132, 2024). "Therefore, we inferred that synaptic dysfunction caused by decreased NCAM2 may play a role in cognitive impairment among COVID-19 patients." (PMID 36211330, 2022). "We identified and positively validated five novel proteins (NCAM2, NPTXR, NRXN2, RELN, and CNTN2) as promising biomarkers for cognitive impairment following aSAH." (PMID 35602555, 2022). "They presented the role of neural cell adhesion molecule 2 (NCAM2) and ICA1L (AD gene marker) in the process leading to cognitive impairment, which may be a potential target for AD intervention." (PMID 36845421, 2023).
Intellectual disability (4 papers, 2021 to 2025). "Genetic variations in the NCAM2 gene are less known but could be the cause of intellectual disability." (PMID 34576185, 2021). "In five cases, the deletion involved only NCAM2, and patients had abnormal phenotypes including those concerning intellectual disability, developmental delay, abnormal facial shape, and seizures." (PMID 34992628, 2021).
Senile plaques (3 papers, 2010 to 2016). Senile plaques are extracellular deposits of amyloid in the gray matter of the brain. "SNPs in the NCAM2 gene also show association with levels of Aβ in the cerebrospinal fluid in humans, suggesting that NCAM2 is involved in the pathogenic pathway to the senile plaques that concentrate in AD brains." (PMID 27242933, 2016). "Our findings suggest NCAM2 could be part of the pathway on the pathogenesis of senile plaques in human brains with AD." (PMID 20932310, 2010).
autism spectrum disorder (2 papers, 2021 to 2022). A spectrum of developmental disorders that includes autism, and Asperger syndrome. "In addition, genetic analyses revealed single nucleotide polymorphisms in NCAM2 gene in patients with abnormal neurodevelopment, Marden–Walker syndrome patients and Autism Spectrum Disorders." (PMID 34576185, 2021).
glioma (2 papers, 2020 to 2024). A benign or malignant brain and spinal cord tumor that arises from glial cells (astrocytes, oligodendrocytes, ependymal cells). "Some regulators of MRM were associated with the expression of NCAM1, NCAM2, and L1CAM, which indicated that MRM may facilitate glioma development via astrocytic modulation." (PMID 38824202, 2024).
prion disease (2 papers, 2010 to 2022). A transmissible disease that is caused by a protein that is able to induce abnormal folding of normal cellular proteins, leading to characteristic spongiform brain changes, which are associated with neuronal loss without an inflammatory response. "C1QA, NCAM2 and PSMA7 were enriched in the prion disease pathway." (PMID 36277688, 2022).
prostate carcinoma (2 papers, 2005 to 2025). A carcinoma that arises from epithelial cells of the prostate gland. "The list of 10 genes again included the well-established prostate cancer markers KLK2, KLK3 (PSA), FOLH1 (PSMA), PSGR (OR51E2), STEAP2, NKX3.1 and Prostein), and also included NCAM2, SPON2 and HOXB13." (PMID 15583692, 2005).
Cirrhosis (1 paper, 2025). A chronic disorder of the liver in which liver tissue becomes scarred and is partially replaced by regenerative nodules and fibrotic tissue resulting in loss of liver function. "NCAM2 was differentially expressed in patients with NAFLD and cirrhosis compared to healthy individuals." (PMID 40489530, 2025).
colorectal cancer (1 paper, 2016). A primary or metastatic malignant neoplasm that affects the colon or rectum. "Other candidates, PARG and TDGF1, have been associated with cancer regulation; however, the functional role of the candidates HORMAD1, PIGC, NCAM2, INO80D, SLCO2A1, SLC12A1, and METTL19 was unclear in colorectal cancer." (PMID 27383761, 2016).
COVID-19 (1 paper, 2022). A disease caused by infection with severe acute respiratory syndrome coronavirus 2. "Moreover, compared to the control group, AD and COVID-19 were associated with a significantly reduced percentage of cluster 3 characterized by neural cell adhesion molecule 1 (NCAM1), neural cell adhesion molecule 2 (NCAM2), and glial fibrillary acidic protein (GFAP)." (PMID 36211330, 2022).
eating disorder (1 paper, 2014). A broad group of psychological disorders with abnormal eating behaviors leading to physiological effects from overeating or insufficient food intake. "Supporting the view of the importance of immune-mediated pathways in the development of eating disorders, a suggestive association with NCAM2 gene, which encodes protein belonging to the immunoglobulin superfamily, was recently found in genome-wide association analysis of AN." (PMID 25147950, 2014).
frontotemporal dementia (1 paper, 2021). Frontotemporal dementia (FTD) comprises a group of neurodegenerative disorders, characterized by progressive changes in behavior, executive dysfunction and language impairment, as a result of degeneration of the medial prefrontal and frontoinsular cortices. "The interaction of NCAM2 with Granulin, GRN, one of the principal proteins associated with familial frontotemporal dementia, suggest a plausible role of NCAM2 as a receptor of the protein and a possible implication in frontotemporal dementia." (PMID 34576185, 2021).
leukemia (1 paper, 2024). A malignant (clonal) hematologic disorder, involving hematopoietic stem cells and characterized by the presence of primitive or atypical myeloid or lymphoid cells in the bone marrow and the blood. "Combined multi-omics data pinpointed three upregulated genes (SDC2, NCAM2, and IFI44) that showed negative effects on survival in a larger leukemia cohort." (PMID 39399221, 2024).
lung squamous cell carcinoma (1 paper, 2022). "Another example is the NCAM2 gene that is enriched with IDR mutations in lung squamous cell carcinoma (LUSC)." (PMID 35061901, 2022).
pregnancy disorder (1 paper, 2025). A disorder that is related to pregnancy. "Specifically, GDM upregulated two genes in male fpEC that were previously linked to other pregnancy disorders, TPTE and NCAM2, respectively." (PMID 41288732, 2025).
cancer (6 papers, 2016 to 2025). A tumor composed of atypical neoplastic, often pleomorphic cells that invade other tissues. "Similarly, seven genes (SGCZ, KANK1, KDM4C, KCNMA1, ZNF263, CDH4, NCAM2) contain partial CNV duplications in both BD‐cancer and BD‐only patients, but the deleted loci are different." (PMID 39140252, 2025). "NCAM2 has been identified as a target molecule in several types of cancers." (PMID 35061901, 2022). "Many of these other potential enhancer-hijacking targets do not have well-established roles in cancer pathogenesis, however, we did notice a number of genes involved in cell adhesion (ALCAM, NCAM2, CADM2, and CDH9) and 2 SLIT and NTRK like family members (SLITRK1, SLITRK6)." (PMID 35538064, 2022).
tumor (6 papers, 2017 to 2024). "We found three down-regulated genes/proteins discriminating BIC-resistant cell lines from LNCaP cells: ADAMTS1, identified as a possible tumor suppressor and two cell adhesion proteins involved in PCa progression, NCAM2 and UTRN." (PMID 29216878, 2017). "Chromosome 1: Nneural cell adhesion molecule 2 (NCAM2) is similar to immunoglobulin superfamily 4 within their Ig-like C2-type domains, which might play role in tumor supression in humans." (PMID 32777913, 2021).
neurodevelopmental disorder (4 papers, 2020 to 2022). A behavioral and cognitive disorder with onset during the developmental period that involves impaired or aberrant development of intellectual, motor, or social functions. "NCAM2 deficiency causes neurodevelopmental disorders in humans via mechanisms that remain poorly understood." (PMID 36251052, 2022). "The neural cell adhesion molecule NCAM2 specifically expressed in RPCs can regulate the differentiation of dendrite and axon, and mutation of the NCAM2 gene causes neurodevelopmental disorders." (PMID 33072724, 2020). "Deletions of the NCAM2 gene are found in individuals with neurodevelopmental disorders, intellectual disability, and autism and other deficits." (PMID 36251052, 2022). "The gene NCAM2 has been proposed to contribute to neurodevelopmental disorders in humans." (PMID 35391799, 2022).
neurodegenerative disease (2 papers, 2021 to 2022). A disorder of the central nervous system characterized by gradual and progressive loss of neural tissue and neurologic function. "In addition, it has been proposed that a decrease in NCAM2 levels is associated with loss of synaptic structure in the early stages of neurodegenerative diseases." (PMID 36457352, 2022). "A decrease in NCAM2 levels and a change in NCAM2 localization in the spine could be associated with loss of structure of synapses in the early stages of neurodegenerative diseases." (PMID 34576185, 2021).
neurological disorders (2 papers, 2021 to 2024). "Thirteen OB proteins were differentially regulated in at least three neurological disorders, of which four of them (NCAM2, LY6H, COL6A3 and PRDX6) presented a homogeneous OB profile across diseases." (PMID 34768771, 2021).
NCAM2 also shares sentences with these, for which no sentence is quoted: brain disorder (1 paper); developmental delay (1); epilepsy (1); fracture (1); gallstones (1); mood disorder (1); Obesity (1); Waldenström macroglobulinemia (1).